NEK7 (NIMA related kinase 7)
Diseases named in the same sentence as NEK7 in open-access papers (continued):
Sharing a sentence is not in itself a finding about the gene and the disease.
infection (8 papers, 2016 to 2024). The state of being infected such as from the introduction of a foreign agent such as serum, vaccine, antigenic substance or organism. "NEK7-mediated pyroptosis has been reported to be involved in immunological diseases and pathogen infection." (PMID 39334337, 2024). "The immunofluorescence staining results showed that RACK1, NLRP3 and NEK7 were diffusely distributed in the cytoplasm in uninfected cells, while PmCQ2 infection induced the colocalization of RACK1 with NLRP3 and NEK7 (white arrows)." (PMID 37684678, 2023). "The results showed that the protein and mRNA expression of NEK7 was reduced in the infection group of J774A.1 cells." (PMID 34603335, 2021). "Western blots confirmed the Nek7 up-regulation at an earlier time point after infection indicating a rapid reaction of the cells due to HSV-1 infection." (PMID 32973653, 2020). "Following infection, real-time PCR and western blot assays were performed to determine Nek7 mRNA and protein expression levels." (PMID 26921196, 2016). "LIF and NEK7 gene expression levels were rescued when the cells had been transfected with miR664i prior to infection." (PMID 27166678, 2016). "RT-qPCR was used to investigate the gene expression levels of miR-664 and predicted host target genes, LIF and NEK7, during infection with H7N9." (PMID 27166678, 2016). "Interestingly, NEK7 was up-regulated already at 8 hours post infection and almost 30 fold up-regulated 20 hpi." (PMID 32973653, 2020). "Taken together our findings in the present research suggest that NEK7 might play different roles in the infection of intracellular bacteria and extracellular bacteria, but we also need to pay attention to the cell cycle during infection." (PMID 34603335, 2021). "Moreover, NEK7 expression at the protein level was markedly decreased in the infection group." (PMID 34603335, 2021). "Furthermore, endogenous coimmunoprecipitation experiments showed that PmCQ2 infection induced the interaction of RACK1 with NLRP3 and NEK7 in macrophages." (PMID 37684678, 2023). "Transcriptional and translational downregulation of NEK7 and TAK1 level in infected cells as compared to control was an interesting finding which led us to design further experimentations to validate the role of NEK7 and TAK1 regulation in host immune surveillance during infection." (PMID 33194842, 2020). "Furthermore, knockdown of Nek7 significantly inhibited the secretion of IL-1β, but the secretion of IL-6, TNF-α, and IL-1α were not affected during PmCQ2 infection." (PMID 35350616, 2022).
cardiovascular diseases (2 papers, 2023 to 2024). "Drugs targeting NEK7 exhibit the highest abundance, while LHX9 only attracts one substance named otenzepad, an acetylcholine receptor antagonist designed to treat cardiovascular diseases, which surprisingly shows effectiveness for NEK7 as well." (PMID 38902711, 2024).
inflammation (2 papers, 2021 to 2024). Aberrant reaction of the microcirculation characterized by movement of fluid and leukocytes from the blood into extravascular tissues. "Our results highlight the importance of myeloid Foxo1 signaling as a key regulator of the NEK7/NLRP3 activation and hepatocyte necroptosis in IR stress-mediated liver inflammation." (PMID 33288903, 2021).
liver (2 papers, 2021 to 2023). "Our findings underscore a novel mechanism of Caspase 6 mediated RIPK1-IκBα interaction in regulating macrophage NEK7/NLRP3 function and hepatocytes ferroptosis, which provides therapeutic targets for clinical liver IR injury." (PMID 37828624, 2023).
disorders of the nervous system (1 paper, 2020). "Since NEK7 has been shown to regulate the formation of neurons in the hippocampus, a region associated with memory, we suggest that NEK7 may be involved in disorders of the nervous system." (PMID 32294979, 2020).
immune dysfunction (1 paper, 2024). "By integrating the MR results, it can be inferred that the gene expression of NEK7 and LHX9 in Activated & resting Treg & CD4 + cell plays a crucial role in carcinogenesis and immune dysfunction." (PMID 38902711, 2024).
NEK7 also shares sentences with these, for which no sentence is quoted: Alzheimer disease (2 papers); Insulin resistance (2); liver cirrhosis (2); rheumatoid arthritis (2); acute kidney injury (1); acute lung injury (1); adenocarcinoma (1); anaplastic thyroid carcinoma (1); bladder cancer (1); brain cancer (1); chronic prostatitis (1); colitis (1); cryopyrin-associated periodic syndrome (1); diabetic foot (1); endometrial cancer (1); endometritis (1); gestational diabetes (1); heart failure (1); Hyperglycemia (1); hyperuricemia (1); leukemia (1); liver inflammation (1); metabolic syndrome (1); non-Hodgkin lymphoma (1); ovarian carcinoma (1); pulmonary fibrosis (1); pulmonary hypertension (1); respiratory failure (1); Streptococcus pneumoniae infection (1).